RET (ret proto-oncogene)
Diseases named in the same sentence as RET in open-access papers (continued):
Sharing a sentence is not in itself a finding about the gene and the disease.
colitis (5 papers, 2017 to 2024). Inflammation of the colon. "This occurs via expression of the neuroregulatory receptor (RET), as ablation of RET in ILC3 leads to reduced IL-22 production and compromised epithelial protection in colon inflammation mouse models." (PMID 31736937, 2019). "In trinitro-benzene-sulfonic acid (TNBS)-induced colitis in rats, glial cell line-derived neurotrophic factor (GDNF) protects enteric neurons from cell death due to metabolic challenges by activating HIF-1α and the REarranged during Transfection (RET) pathway." (PMID 38605960, 2024). "In a retrospective, multicenter study, ICI was used as second-line or later treatment for 9 patients with advanced RET fusion NSCLC, and the researchers reported that 10% of the enrolled patients experienced 3–5 grade immune-mediated adverse events (AEs) (most commonly colitis)." (PMID 39669196, 2024). "Similarly in PLP1CreER:tdT mice, PLP1 cells that co-express S100b but not RET also give rise to neurons following colitis." (PMID 28566702, 2017).
colon adenocarcinoma (5 papers, 2014 to 2023). "RET expression is relatively low in colon adenocarcinoma and several studies have noted frequent methylation of the RET promoter, suggesting reduced RET expression may be associated with worse prognosis in some cases." (PMID 30666215, 2018). "We observed an FGFR2 fusion from the ASC supernatant in gastric adenocarcinoma and a RET fusion in colon adenocarcinoma tissues." (PMID 36167530, 2022). "RET chimeric oncoproteins are rare (0.2–0.5% cases), but promote tumor growth and migration in animal and cell based models and have been correlated with worse prognosis, poor treatment response and reduced overall survival in colon adenocarcinoma patients." (PMID 30666215, 2018). "Of note, 41.7% (25/60) of the RET fusion-positive colon adenocarcinomas had an MSI-H status which was significantly higher than the RET fusion negative colon adenocarcinoma (5.5%, 1805/32,938) (p < 0.001)." (PMID 36690680, 2023).
Ewing sarcoma (5 papers, 2016 to 2023). A small round cell tumor that lacks morphologic, immunohistochemical, and electron microscopic evidence of neuroectodermal differentiation.
mesothelioma (5 papers, 2017 to 2026). A usually malignant and aggressive neoplasm of the mesothelium which is often associated with exposure to asbestos. "In contrast, some types of cancers including, but not limited to, kidney renal papillary cell carcinoma (KIRP), tenosynovial giant cell tumor (TGCT), thymoma (THYM) and mesothelioma (MESO) were barely detected with any RET mutations." (PMID 35978072, 2022). "Whereas the higher rate of overexpression in two target genes (CDKN2A and RET) represent high OS and lower expression show the small OS time in mesothelioma." (PMID 36139498, 2022).
metastasis (5 papers, 2020 to 2025). The spread or migration of cancer cells from one part of the body (where they first appeared) to another. "In term of clinicopathological markers, the NCOA4::RET rearrangement was significantly associated with angioinvasion (p = 0.001), lymphatic invasion (p = 0.003), extrathyroidal extension (p = 0.001), lymph node metastasis (p < 0.001) and extranodal extension (p = 0.013), respectively." (PMID 37188126, 2023). "Our FISH analysis and NGS results indicate that, in this patient, the RET gene fusion was expressed in a large proportion of tumor cells in a PTC-rich lymph node metastasis and was also present in the ATC cells of a neck metastasis detected at the time of disease progression." (PMID 32292131, 2020). "The prevalence of CNS metastasis in patients with specific genomic alterations was the following: ALK (34.9%), RET (32.2%), KRAS (30.2%), EGFR (29.4%), and wild type (28.8%)." (PMID 40423053, 2025).
neuropathy (5 papers, 2016 to 2025). A disorder affecting the nervous system that manifests with pain, tingling, numbness, and/or muscle weakness. "However, RET is expressed in the adult peripheral nervous system and treatment with this agent is also associated with on-target neuropathy." (PMID 27602955, 2016). "In our pilot experiments we consistently saw a decrease in the area and/or number of IBA1-positive cells in DRGs of animals with experimental neuropathies treated with ARTN or RET agonists compared to the values seen in DRGs of animals treated with vehicle." (PMID 34220453, 2021). "The treatment with a RET agonist, compound BT44, which started 2 days after the surgery when neuropathy was already established, partially normalized this change, although statistically significant decrease was not seen." (PMID 34220453, 2021). "Proposed sequence (for testing): molecular screening; short-course TRK/RET inhibition to debulk; add CSF1R blockade to shift macrophages; consider β-blockade plus PD-1/PD-L1 for maintenance; monitor neuropathy, hepatic AEs, QT, and paediatric growth-plate changes." (PMID 41142827, 2025).
skin cancer (5 papers, 2020 to 2025). "Previous studies have demonstrated RET's genotoxicity in vitro and zebrafish models, while in silico analysis further supports its involvement in skin cancer development." (PMID 40211435, 2025). "While the primary focus of RET inhibitors has been on lung and thyroid cancers, their application in skin cancers like AK and cSCC is an area of interest." (PMID 39925808, 2025). "In the 4th edition of the 2018 WHO classification of skin tumors, lesions in the spitzoid pathway (pathway 4) are characterized by mutations in HRAS, tyrosine kinase fusions (ALK, ROS1, RET, NTRK1/3, and MET), or serine-threonine kinase fusions (BRAF, MAP3K8)." (PMID 33040161, 2021). "To compare the immunosuppressive pattern of PMN-MDSC and M-MDSC, we determined the frequency of PD-L1, CD39, and CD73 and the level of their expression (detected as mean fluorescence intensity, MFI) in skin tumors of RET transgenic mice." (PMID 33578808, 2021). "The exploration of RET inhibitors in skin cancers is still in its early stages." (PMID 39925808, 2025).
small cell lung carcinoma (5 papers, 2018 to 2024). Small cell lung cancer (SCLC) is a highly aggressive malignant neoplasm, accounting for 10-15% of lung cancer cases, characterized byrapid growth, and early metastasis. "Histological transformation into small cell lung cancer was a new mechanism of acquired resistance to RET TKIs." (PMID 38057798, 2023).
spindle cell tumors (5 papers, 2022 to 2026). "Undifferentiated spindle cell neoplasms with NTRK-rearrangement (or activating mutations in RAF1, BRAF, RET, MET, and others) are rare, recently described lesions in children." (PMID 40491214, 2025). "Here, we describe a case of RET rearranged spindle cell tumor in a 3-year-old girl who presented with swelling and pain in the arm." (PMID 40873555, 2025). "Recently, a novel group of CD34 and S100 co-expression spindle cell tumors with distinctive stromal and perivascular hyalinization harboring recurrent gene fusions involving RET, RAF1, BRAF, and NTRK1/2 gene has been identified." (PMID 36229858, 2022).
adrenal pheochromocytoma (4 papers, 2013 to 2024). "Since then, the patient was diagnosed with bilateral adrenal pheochromocytoma with a RET proto-oncogene mutation and a bilateral medullary spongy kidney." (PMID 37335636, 2023). "The patient was diagnosed with bilateral adrenal pheochromocytoma with a RET proto-oncogene mutation and a bilateral medullary spongy kidney." (PMID 37335636, 2023).
chordoma (4 papers, 2022 to 2024). Chordomas are rare malignant tumors arising from embryonic remnants of the notochord in axial skeleton. "The clinical manifestations of RET variants located in codon 804 are variable even within families, but chordomas have never been reported as part of the phenotype." (PMID 38700789, 2024).
colorectal tumors (4 papers, 2017 to 2023). "By comparing ponatinib activity in RET fusion-positive and RET fusion-negative PDX models alongside a standard of care chemotherapeutic agent, we show that RET fusions in colorectal tumors are therapeutically responsive to RET inhibition." (PMID 30038711, 2018). "There were no instances of MSI in 56 non-colorectal tumors carrying ALK, ROS1, RET or NTRK1 rearrangements." (PMID 37686416, 2023).
cryptorchidism (4 papers, 2011 to 2020). The failure of one or both testes of a male fetus to descend from the abdomen into the scrotum during the late part of pregnancy. "Among the eighteen genes, four have been previously identified in patients with hypospadias (CYP1A1, FLNA, GLI3, and GLI2), three have been reported to be associated with cryptorchidism (FLNA, RET, and PTPN11), and one has been identified in patients with micropenis (EVC)." (PMID 33424767, 2020).
follicular adenoma (4 papers, 2017 to 2023). "Positive testing for BRAF or RET/PTC mutation has been shown to be specific for a malignant outcome in 100% of cases, whereas RAS mutations have been detected in up to 48% of benign follicular adenomas, 57% of FTC, and 21% of PTC." (PMID 35625691, 2022). "In contrast, RAS mutation was identified in eight nodules, of which four were malignant, and one RET/PTC3 rearrangement in a follicular adenoma." (PMID 32638211, 2021). "These 17 patients were subjected to surgery and 15/17 (88.2%) were confirmed malignant at final histology (3 FTC, 5 PTC and 7 follicular variant PTC) whereas 2/17 (11.7%) were follicular adenoma (1 NRAS and 1 RET/PTC)." (PMID 28383480, 2017). "Last, one RET/PTC3 rearrangement was detected in a follicular adenoma." (PMID 32638211, 2021).
hereditary cancer (4 papers, 2018 to 2023). Malignant neoplasms occurring in families at a rate greater than that expected by chance and caused by germline mutations in a specific gene. "In contrast to numerous inactivating mutations in tumor suppressor genes, activating mutations contributing to familial cancer are rare and include the genes RET, MET, KIT, and ALK." (PMID 33916261, 2021).
inflammatory myofibroblastic tumor (4 papers, 2021 to 2024). A multinodular intermediate fibroblastic neoplasm that arises from soft tissue or viscera, in children and young adults. "Inflammatory myofibroblastic tumor fusions involving ROS1, PDGFRβ, RET, and NTRK have also been described in inflammatory myofibrosarcoma." (PMID 35865478, 2022).
liposarcoma (4 papers, 2015 to 2018). A usually painless malignant tumor that arises from adipose tissue. "One factor that has been implicated in liposarcoma is the protooncogene rearranged during transfection (RET)." (PMID 25749382, 2015). "Since RET has been implicated in liposarcoma, it is considered a potential therapeutic target." (PMID 25749382, 2015). "Accordingly, knockdown of SPIN1 or MAZ results in reduced levels of GDNF and activated RET explaining diminished liposarcoma cell proliferation and survival." (PMID 25749382, 2015). "Our mechanistic studies in vitro and in xenograft mouse models demonstrate that SPIN1, in cooperation with the transcription factor MAZ, controls proliferation and apoptosis of liposarcoma cells by directly regulating expression of the RET signaling pathway effector GDNF." (PMID 25749382, 2015). "Thus, SPIN1 controls target gene expression, proliferation, and apoptosis by modulating RET signaling in liposarcoma." (PMID 25749382, 2015). "In summary, our data demonstrate that SPIN1 controls proliferation and survival of liposarcoma by regulating GDNF expression and thereby RET activation." (PMID 25749382, 2015). "Our data provide evidence that SPIN1 controls liposarcoma cell proliferation and apoptosis by directly enhancing the expression of GDNF, an activator of the RET signaling pathway." (PMID 25749382, 2015). "Analysis of 155 patient samples revealed that levels of GDNF, activated RET (RETph), and MAZ were elevated in all four types of liposarcoma." (PMID 25749382, 2015). "In accordance with these results, we observe increased levels of GDNF, activated RET, and MAZ in human liposarcoma compared to normal adipose tissue or lipoma." (PMID 25749382, 2015). "Thus, SPIN1 knockdown reduces liposarcoma cell-derived tumor growth in mice, which correlates with reduced levels of both GDNF mRNA and RET phosphorylation." (PMID 25749382, 2015).
meningioma (4 papers, 2021 to 2025). A generally slow growing tumor attached to the dura mater. "The RET splice variant (c.1880-2A>C) found in both meningioma tumours is reported (rs193922699) as likely pathogenic in the Single Nucleotide Polymorphism Database (dbSNP)." (PMID 38476782, 2024). "Three meningiomas, all recurring within 68 months of follow-up, had RET alterations, consisting of an R982C mutation in two cases (13M; 22M) and a Y791F mutation in one case (14M)." (PMID 33670055, 2021).
metastatic colorectal cancer (4 papers, 2015 to 2026). "RET fusions are rare but actionable oncogenic drivers in metastatic colorectal cancer (mCRC), occurring in a small molecular subset with limited clinical evidence for selective RET inhibition." (PMID 42187588, 2026). "RET fusions have been reported in patients with metastatic colorectal cancer (mCRC)." (PMID 34741450, 2021). "Through comprehensive genomic profiling we prospectively identified 6 RET fusion kinases, including two novel fusions of CCDC6-RET and NCOA4-RET, in metastatic colorectal cancer (CRC) patients." (PMID 26078337, 2015).
pancreatic adenocarcinoma (4 papers, 2018 to 2025). "Out of 160 pancreatic adenocarcinoma samples examined, only a single case was found to have a RET rearrangement, resulting in a prevalence rate of 0.6%, thus highlighting the rarity of such genetic alterations in pancreatic cancer." (PMID 39085487, 2024). "In human pancreatic adenocarcinoma tissues and MiaPaCa-2 cell lines, binding of GDNF to its receptor GFRα1 stimulates PNI via GDNF-(Ret proto-oncogene) RET signaling pathway." (PMID 29334991, 2018). "On the contrary, high RET expression resulted in better OS in patients with esophageal carcinoma (ESCA), LUCA, pancreatic adenocarcinoma (PAAD), and THCA." (PMID 35978072, 2022).
pneumonitis (4 papers, 2023 to 2024). An inflammatory process affecting the lung parenchyma. "Pneumonitis and drug-induced interstitial lung disease (ILD) can occur with RET inhibitors, especially with pralsetinib." (PMID 38118420, 2023).
prostate adenocarcinoma (4 papers, 2014 to 2023). "This is consistent with our previous work demonstrating that NEPC cell lines have a stronger dependency on RET than prostate adenocarcinoma cell lines." (PMID 37065756, 2023). "A recent study from Justin Drake's lab has showed that RET phosphopeptides and mRNA levels are higher in NEPC than in prostate adenocarcinoma, while RET inhibitor AD80 blocks NEPC cell growth in culture and in mouse xenografts." (PMID 32039001, 2019). "The discrepancy of RET and ZBTB7A dependency in SCN HI versus SCN LO cell lines indicated that these genes may exhibit distinct gene interactions in NEPC compared to prostate adenocarcinoma." (PMID 37065756, 2023).
salivary duct carcinoma (4 papers, 2022 to 2026). An aggressive, high grade adenocarcinoma that arises from the salivary glands. "Genomic profiling salivary duct carcinomas (SDCs) reveals that RET is frequently altered in this tumor type, with three clinical cases presenting with RET fusion products, CCDC6-RET or NCOA4-RET." (PMID 35957881, 2022).
T-cell lymphoma (4 papers, 2012 to 2022). "RET is a transmembrane receptor tyrosine kinase, which is coded by proto-oncogene RET, and was first discovered in T cell lymphoma." (PMID 36358717, 2022). "With this aim, and aware that the inhibition of RET has always been a challenge since its discovery in T-cell lymphoma, we want to summarize the available knowledge on RET inhibitors, including both ongoing trials with new drugs and pre-clinical data concerning overcoming the resistance mechanisms." (PMID 33806299, 2021).
Thrombocytopenia (4 papers, 2022 to 2024). A reduction in the number of circulating thrombocytes. "Blood and lymphatic system disorders are frequent found during RET-inhibitors treatment, including anemia, lymphopenia, leukopenia and thrombocytopenia, of which anemia is the most common event." (PMID 39372206, 2024). "Lu conducted a retrospective analysis of 38 patients treated with selective RET inhibitors and found that 31.6% developed neutropenia, thrombocytopenia, lymphocytopenia, or anemia." (PMID 37603207, 2023).
acute lymphoblastic leukemia (3 papers, 2014 to 2022). Leukemia with an acute onset, characterized by the presence of lymphoblasts in the bone marrow and the peripheral blood. "A second potential repurposing target for acute lymphoblastic leukemia is the oncogene RET." (PMID 25057111, 2014). "We report the case of a patient with B-Cell Acute Lymphoblastic Leukemia (ALL) who was found to harbor a gene fusion involving the CCDC6 and RET genes." (PMID 31850206, 2019).
adrenal tumors (3 papers, 2017 to 2023). "Considering the location of the tumour; intra-adrenal tumours suggest possible RET, VHL, NF1, TMEM 127, MAX or rarely KIF1B mutations." (PMID 29166454, 2017). "Although, rare extra adrenal tumours can also be found in VHL, TMEM 127, NF1, and RET mutations as well." (PMID 29166454, 2017).
angiosarcoma (3 papers, 2018 to 2022). A malignant tumor arising from the endothelial cells of the blood vessels. "The importance of EGFR was suggested in a study of a cell line derived from a radiation-associated angiosarcoma where inhibition of the VEGFR2/EGFR/RET axis resulted in decreased cell proliferation." (PMID 29515789, 2018).
bladder cancer (3 papers, 2014 to 2025). "We also identified the RET kinase pathway, targeted by AST-487, as a novel regulator of mutant hTERT promoter-driven transcription in bladder cancer cells." (PMID 36142729, 2022).
brain cancer (3 papers, 2015 to 2025). A primary or metastatic malignant neoplasm affecting the brain. "Since 2009, the FDA has approved a number of multi-kinase inhibitors that target angiogenic growth factor receptors (e.g., VEGFR, PDGFR, FGFR, RET, c-KIT, MET, AXL and others) for treatment of malignant diseases, including brain cancer." (PMID 40076810, 2025).
cervical carcinoma (3 papers, 2015 to 2023). A carcinoma arising from either the exocervical squamous epithelium or the endocervical glandular epithelium.